HTRA4 (HtrA serine peptidase 4)
Diseases named in the same sentence as HTRA4 in open-access papers (continued):
Sharing a sentence is not in itself a finding about the gene and the disease.
cancer (5 papers, 2014 to 2024). A tumor composed of atypical neoplastic, often pleomorphic cells that invade other tissues. "Taken together, these results indicate that the full-length HtrA4 and its N-terminally deleted variant promote cancer cell death induced by chemotherapeutic drugs." (PMID 31546993, 2019). "HTRA4 is a human protease implicated in various tumors, including BC, which has been associated with oncogenesis and demonstrated to promote cancer cell death and apoptosis induced by the enhanced activity of chemotherapeutic drugs in BC cell lines, and is a potential prognostic biomarker for BC." (PMID 38672084, 2024). "Thus, it is possible that the degradation of XIAP by HtrA4, in order to promote apoptosis, needs other pro-apoptotic events to occur in parallel, especially in the cancer cells that usually have mutations inhibiting apoptosis." (PMID 31546993, 2019). "Studies have explored the potential role of HtrA4 in cancer cell lines, reporting that HtrA4 promotes cell death by degrading XIAP and pro-caspase 7, which was shown previously for HtrA1 and 3 in cancer cells." (PMID 34639128, 2021). "In this work, we show for the first time that HtrA4 promotes death of cancer cells treated with chemotherapeutic drugs, mainly via apoptosis." (PMID 31546993, 2019). "In conclusion, these results showed that HtrA4 promotes death of the chemotherapeutic drug-treated cancer cells by enhancing apoptosis." (PMID 31546993, 2019). "Since the HtrA4 protein affected cell survival, we investigated its influence on clonogenic potential and motility of cancer cells treated with chemotherapeutics." (PMID 31546993, 2019). "Since HtrA4 stimulates drug-induced death of cancer cells, this protease seems to be a promising therapeutic target." (PMID 31546993, 2019). "Collectively, these results show that HtrA4 enhances the activity of chemotherapeutics by decreasing survival of cancer cells as well as their clonogenic potential and motility, and the latter are tightly connected with metastasis." (PMID 31546993, 2019). "Summing up, these results indicate that HtrA4 is an important factor that enhances the influence of drugs routinely used in chemotherapy on clonogenic potential and motility of cancer cells, and it increases blocking of cell cycle at the G2/M phase." (PMID 31546993, 2019). "Subsequently, in this work, we for the first time showed that HtrA4 reduces survival of adenocarcinoma cells treated with chemotherapeutic drugs and promotes cancer cell death by enhancing apoptosis." (PMID 31546993, 2019). "These included several candidate tumor suppressor genes, such as ABLIM1, CYFIP2, VPS13A, SERPINI1, TET2, HTRA4, UBE2L6, as well as oncogenes/genes implicated as biomarkers in other cancers, such as FAM65B and TCF7L2." (PMID 27385100, 2016). "We found that HtrA4 reduced survival, clonogenic potential, and motility of cancer cells." (PMID 31546993, 2019). "Furthermore, HtrA4 increases the effect of chemotherapeutics on the clonogenic potential and motility of cancer cells, and it increases cell cycle arrest at the G2/M phase." (PMID 31546993, 2019). "Moreover, we demonstrated that exogenous production of HtrA4 and ∆N-HtrA4 attenuated the clonogenic potential and motility of cancer cells treated with etoposide, and it modulated the cell cycle by enhancing arrest of the cells in the G2/M phase." (PMID 31546993, 2019). "However, the high similarity of the HtrA4 protein domain structure to that of HtrA1 and HtrA3, and implication of HtrA4 in oncogenesis suggest that it may function similarly to HtrA1/3 in promoting cancer cell death." (PMID 31546993, 2019). "The results showed that the exogenous production of either HtrA4 or ΔN-HtrA4 significantly decreased survival of the drug-treated cancer cells compared to the control, noninduced cells." (PMID 31546993, 2019).
adenocarcinoma (1 paper, 2019). A common cancer characterized by the presence of malignant glandular cells. "A549 adenocarcinoma cells were used because they contained a relatively low level of endogenous HtrA4." (PMID 31546993, 2019).
cardiovascular disease (1 paper, 2021). "HtrA4 significantly upregulates senescence genes while downregulating those responsible for cell cycling and DNA repair, suggesting that high levels of circulating HtrA4 may promote endothelial cell senescence and aging, which are major risk factors of cardiovascular disease." (PMID 34639128, 2021).
HTRA4 also shares sentences with these, for which no sentence is quoted: brain tumors (1 paper); gestational diabetes mellitus (1); lung adenocarcinoma (1).